CASP9 (caspase 9)
Diseases named in the same sentence as CASP9 in open-access papers (continued):
Sharing a sentence is not in itself a finding about the gene and the disease.
cancer (continued). "Compared to immune and stroma cells, cancer cells showed higher entropy in levels of BAK, BAX, PRO-CASPASE 9, SMAC, and XIAP (ANOVA p < 0.05, Tukey post-hoc p < 0.05)." (PMID 34754079, 2022). "Among these signatures (TNF, TIRAP, CASP9, PLCG1, PRKACA, CASP3, CASP8, CASP4), TNF (Tumor necrosis factor) is currently considered a two-edged sword in cancer development." (PMID 35741587, 2022). "In several human cancer cell lines, DYRK1A has been shown to act as a caspase-9 Thr125 kinase, inhibiting intrinsic apoptotic pathways." (PMID 35053488, 2022). "The results showed that the expressions of caspase-3 and caspase-9 in MGF group were higher than those in MT group, which suggested that MGF and MT achieved anti-cancer effect by inducing apoptosis, and the effect of MGF was better than MT." (PMID 36386222, 2022). "Although in different cancer settings, previous studies reported inhibition of p38 MAPK-triggered apoptosis via activation of caspase-8 and/or caspase-9." (PMID 35681235, 2022). "Furthermore, coding variants A28V/G (rs1052571) and Q221R (rs1052576) are still not characterized for how they may impact caspase-9 signaling, despite extensive associations of these mutants with multiple cancers and degenerative and inflammatory pathologies." (PMID 34305609, 2021). "To gain an understanding of the reason that the anti-cancer capacity of TmSm34/48/84 was weaker than that of TmSm34/84, we used ZDOCK to simulate the docking for three multisite TmSm proteins with caspase-9." (PMID 33869021, 2021). "When cancer cells were pretreated with BLT-1 for 3 hr and then treated with HDL, caspase-9 activity decreased significantly." (PMID 34804424, 2021). "Badmus and others reported a low caspase 9 induction effect of Holarrhena floribunda (G. Don) extracts on the breast (MCF-7), colorectal (HT-29), and cervical (HeLa) cancer cells." (PMID 32308718, 2020). "As the caspase cascade plays a regulatory role in the apoptosis of various cancer cell lines, we examined the effect of CP-Mh on the expression of key molecules of the apoptotic signaling cascade, including Bax/Bcl-2 ratio, BID, Casp-9 and Casp-3." (PMID 33158052, 2020). "In the current study, we observed that treatment of cancer cells with DCM and MeOH extracts of S. amplexicaulis led to a decrease in the mRNA expression levels of Bcl-2 and increases in p-53, caspase-3, caspase-9, and Bax." (PMID 33122979, 2020). "The majority of strong indirect interactions pointed to the 3 key apoptosis proteins CASP9, CASP3 and APAF1 (apoptotic protease activating factor) whose local PageRanks decreased in the “cancer” network (which means they become more regulated)." (PMID 29370181, 2018). "In the present study, we showed that HHT could regulate the alternative splicing of Bcl-x and Caspase 9, resulting in a decrease in the levels of anti-apoptotic Bcl-xL and Caspase 9b mRNA with a concomitant increase in the mRNA levels of pro-apoptotic Bcl-xS and Caspase 9a in several cancer cells." (PMID 29788973, 2018).
cancer (continued). "The intrinsic apoptosis-related transcripts (BAX, caspase 3 and caspase 9) and stress-related transcripts (p21, HSP70 and HSP90) were broadly detected at a low level in untreated control A-549, MDA-MB-231 and U87-MG cancer cells." (PMID 30460075, 2017). "To gain insight into the mechanism by which VP + SF eliminates cancer cells, we evaluated the expression of key proteins involved in apoptosis (PARP, caspase 3, and caspase 9), autophagy (Beclin-1 and p62), and necroptosis (RIP1 and MLKL)." (PMID 29201061, 2017). "Other reported targets of miR-24 include proapoptotic (FAF-1, Caspase-9, Bim, and Apaf-1) and cell cycle proteins; miR-24 was also shown to regulate XIAP, reducing the threshold for apoptosis in cancer cells." (PMID 28061479, 2017). "Effect of compounds 5e and 10g on active caspase-9 and -3 levels, and the expression levels of Bcl-2 and Bax in MDA-MB-231 cancer cells treated with the compounds at their IC50 concentrations." (PMID 28173708, 2017). "Here in our results, the active caspase-9, caspase-8, caspase-3, and PARP, were remarkably increased by AZOX in KYSE-150 cells, indicating that the apoptosis pathway is one of the anti-cancer mechanisms of AZOX." (PMID 28567017, 2017). "COTI-2 treatment reduced p-AKT and p-caspase-9 levels in SHP-77 cells, further establishing its role in inducing apoptosis via caspase pathways in cancer cells." (PMID 27150056, 2016). "Consistent with this, we assessed the mRNA expression levels of SIRT1, EFNB3, and several apoptosis-regulating genes (BIK, CASP3, CASP4, and CASP9) in MCF-7 and MDA-MB-231 cancer cells." (PMID 24489730, 2014). "In analyzing the mechanism of PTS2-induced apoptosis, we found PTS2 treatment induced cleavage of caspase-9, caspase-3 and PARP in cancer cells, which implies that activation of caspase-9, caspase-3 and PARP is involved in PTS2-induced cell death." (PMID 24139500, 2013). "We demonstrated that DPT-C9h specifically target caspase-9/PP2A interaction in vitro and in vivo and induced caspase-9-dependent apoptosis in cancer cell lines." (PMID 23637769, 2013). "Here, we report novel toxicity of PTS2 on various cancers, and show PTS2 to inhibit proliferation of four cancer cell lines and induce apoptosis involving activation of caspase-9, caspase-3 and PARP." (PMID 24139500, 2013). "This suggests that cleavage of caspase-9, caspase-3 and PARP are involved in PTS2-induced cancer cell apoptosis." (PMID 24139500, 2013). "Our data revealed that Bcl-2 denitrosylation induced by ZD55-IL-24 triggered the activation of caspase-9, caspase-3, PARP and final carcinoma cell apoptosis from the results of western blotting and flow cytometry." (PMID 22629368, 2012). "Western blot analysis showed that treatment with 1 μM NSC-743380 effectively activated caspase-8 and caspase 9 in MCF-7 and A498 cells, indicating that its cytotoxic effect in cancer cells is due to its induction of apoptosis." (PMID 22174819, 2011). "However, mutations in either Caspase-9 or Apaf-1 have not been commonly identified in cancers." (PMID 21611191, 2011). "More specifically, raw crushed garlic is high in allicin, a powerful bioactive compound of garlic that induced activation of CASP3, CASP8 and CASP9 and cleavage of poly (ADP-ribose) polymerase in several cancer cells." (PMID 19552815, 2009). "In different cancers, activation of Akt acts by phosphorylation of transcription factors, signalling components such as IKK, caspase 9, mTor, Bad and others." (PMID 16721361, 2006). "We show here that declopramide at doses above 250 μM in the mouse 70Z/3 pre-B cell line or in the human promyeolocytic cancer cell line HL60 induced cytochrome c release into the cytosol and caspase-9 activation." (PMID 11953831, 2002).
cancer (continued). "The chloroform extract also displayed potent anticancer activity, characterized by nuclear condensation, activation of caspase-9 and caspase-7, cleavage of Poly (ADP-ribose) polymerase (PARP), and upregulation of Bax, thereby inducing apoptosis in cancer cells." (PMID 41781719, 2026). "• Exertion of anticancer effects through 3 major pathways: apoptosis (BIRC3, BIRC5, caspase-8, caspase-9, and PARP1), transcriptional dysregulation in cancer (CDKN1A, CDKN1B, MMP9, MYC, JUN, and RELA), and cancer progression (caspase-3, CCND1, CTNNB1, VEGFA, and Wnt-1)." (PMID 39181121, 2025). "Furthermore, gene expression analyses revealed significant upregulation of caspase 9 and key alterations in cancer‐related genes, including Bcl‐2, Bax, and GAPDH, implicating the caspase 9‐mediated apoptotic pathway as a central mechanism of action." (PMID 40079412, 2025). "In HT-29 cancer cell lines, Caspase-3/7 activity increased, while Caspase-8 and Caspase-9 activity decreased compared to the negative control." (PMID 40872562, 2025). "RO-treated animals showed delayed malignant transformation, with no carcinomas at week 16 and increased expression of caspase-9, calreticulin, HMGB1, IFN-γ, and GM-CSF, indicating transient activation of antitumor immune responses." (PMID 40943044, 2025). "The most pronounced differences between the cell lines included the induction of cell death (via the activation of caspase 7 and caspase 9 and PARP1 cleavage) and the inhibition of the estrogen response signaling pathway in the estrogen receptor-positive MCF7 cancer cell line." (PMID 39468555, 2024). "Similarly, for cancer (Ca9-22) and normal (S-G) cells, the X-ray and/or SK2 treatment exhibited higher activated caspase 9 (+) (%) than the control." (PMID 38398060, 2024). "Our findings showed that BHE and betanin can stimulate the intrinsic and extrinsic apoptosis pathways in HT-29 and Caco-2 cancer cell lines via downregulation of Bcl-2 and upregulation of BAD and Caspase-9 genes and also upregulation of Fas-R, Caspase-3, and Caspase-8, respectively." (PMID 37464362, 2023). "To further detect the mechanisms behind the apoptotic process induced by treatments using either QU or CDDP and QU pre-treatment, we investigated the expression of specific apoptosis marker proteins (cleaved caspase-9,7,3 and cleaved PARP) with Western blot in both cancer cells." (PMID 37446140, 2023). "LaSota is a lentogenic strain investigated for its potential to induce significant anti-cancer effects in MCF7 and Arabian and Middle Eastern breast cancer cell lines (AMJ13), mainly via the intrinsic apoptotic pathway, as the percentage of caspase-9 was found to be higher than that of caspase-8." (PMID 37629483, 2023). "The results show that expression of ELANE, PRKACA, CASP3, CASP9 and CASP6 was related to the efficacy of various anticancer drugs, indicating that pyroptosis genes may participate in pan‐cancer signalling pathways and affect the efficacy of anticancer drugs." (PMID 34816605, 2022). "This heptapeptide could induce apoptosis of cancer cells, probably due to its interaction with XIAP, which liberates caspase-9 from the inhibitory complex with XIAP and facilitates its activation." (PMID 36360120, 2022). "Moreover, another IAP inhibitor, DEBIO1143 promotes apoptosis of cancer cells by mimicking the structure and activity of SMAC, which can block the XIAP and reactivate the caspase-9." (PMID 34026617, 2021).
cancer (continued). "After 6 h, the total protein was extracted for phosphorylation protein microarray analysis, which found that AKT and GSK3β protein phosphorylation ratios in the sh-cancer-IgG group were reduced and that Bcl-2, BAD, caspase 3, caspase 9, and BAX apoptosis-related proteins increased." (PMID 34150640, 2021). "Excessive ROS mediates the programmed cell death cascade, including caspase-3, caspase-9, and PARP cleavage, in various cancer types, and it may provide a powerful anti-cancer therapy strategy." (PMID 34830138, 2021). "Low doses of BTZ enhanced the anti-cancer effect induced by the low dose of BGB-3111 by downregulating the expression levels of PARP and Bcl-2 and increasing the expression levels of cleaved PARP and cleaved caspase-9." (PMID 34508613, 2021). "Moreover, we found that the combination of low-dose BGB-3111 with low-dose BTZ significantly enhanced the anti-cancer effects by increasing the expression of cleaved PARP and caspase-9 and inhibiting Bcl-2 expression and further affecting the NF-κB pathway." (PMID 34508613, 2021). "In cancer and cardiomyocytes, ADRB2 inhibits apoptosis mainly through Bcl-2/Bax/caspase-9 pathway." (PMID 31781263, 2019). "Caspase-8 and caspase-9 knockdown in HCT116 cells inhibited caspase-3 activity confirming the involvement of both of the initiator caspases in Api and TG combination treatment-induced apoptotic cell death in cancer cells." (PMID 31673102, 2019). "Previous studies have suggested that curcumin could activate caspase-3, caspase-8, and caspase-9 and PARP protein in various cancer cell lines." (PMID 31687403, 2019). "Aloe-emodin reduces cancer cell viability through extrinsic (TNF-a and FASL) and intrinsic (cytochrome c/caspase 9) apoptosis pathways, which coincide with deleterious effects on mitochondrial membrane permea-bility and/or oxidative stress via exacerbated ROS production." (PMID 30895270, 2018). "Activation of caspase-3 and caspase-9 was preceded by the disturbance of the mitochondrial membrane potential, which occurred in a time-dependent manner, and by the generation of ROS in the cardol-treated SW620 cancer cells." (PMID 28472978, 2017). "Furthermore, pro-apoptotic gene transcription, including, Bax, caspase 9 and caspase 3, is also abrogated in MRC-5 cells in comparison with all the cancer cell lines." (PMID 28797070, 2017). "Cellular apoptosis proven by DNA fragmentation was observed, and intrinsic apoptotic transcripts (BAX, caspase 3 and caspase 9) and stress-related transcripts (p21, HSP70 and HSP90) were significantly (P < .05) increased in three cancer cell lines treated with SMA." (PMID 30460075, 2017). "Since TRAIL enhances apoptosis in cancer, we determined whether apoptosis would be detected after AAA induction by immunohistochemical detection of Caspase-9, a marker of apoptosis." (PMID 26783750, 2016). "DYRK1A has been shown to suppress caspase-9-mediated apoptosis in mammalian cells through phosphorylation of caspase-9 on threonine residue 125.22, 23 These findings suggest that SAHA and DZNep induce DYRK1A-mediated apoptosis in cancer cells through activation of miR-1246." (PMID 24861464, 2014). "To further investigate CTLA4-FasL mode-of-action in cancer cell line, we studied if CTLA4-FasL cytotoxic effect can be abrogated by the pan-caspase inhibitor (Z-VAD), caspase 8 inhibitor (Z-IETD-FMK) and caspase 9 inhibitor (Z-LEHD-FMK) on malignant cell lines positive for Fas only." (PMID 25227919, 2014). "To see whether PTS2-induced cell death involved activation of caspases and PARP, we analyzed cleavage of caspase-9, caspase-3 and PARP in PTS2-treated cancer cells." (PMID 24139500, 2013). "DNA damage was also observed in cancer cells which is known to activate Caspase-9 leading to intrinsic apoptosis in the absence of mitochondrial-mediated pathway." (PMID 24305113, 2013).
cancer (continued). "Bax/Bcl-2 may have an effect on caspase-3 by enhancing apoptosis of cancer cells by cytochrome c, APAF-1, caspase-9 and other death substrates." (PMID 22266878, 2012). "Importantly, PTX increases the sensitivity of cancer cells to the toxic effects of ADR by caspase participation and regulation of caspase -3, caspase-9, puma, noxa, and diablo genes." (PMID 20482878, 2010). "Overexpression of Bcl-2, cytokeratins, and VEGF with downregulation of Bax, cytochrome C, caspase-3, caspase-9 and PARP may confer a survival advantage to HBP carcinomas by acquisition of an apoptosis-resistant, invasive and angiogenic phenotype." (PMID 18053169, 2007). "In addition, HSP decreases Bcl-2, mitochondrial AIF, mitochondrial Apaf-1, and mitochondrial cyt-c, which drive cancer cell apoptosis, while upregulating a few intracellular ROS, ATP, Ca2+, and cytosolic components such as AIF, Apaf-1, cyt-c, caspase-3, caspase-9, and Bax." (PMID 40427522, 2025). "EGCG promotes apoptosis in cancer cells through various mechanisms, including the inhibition of the Epidermal Growth Factor receptor (EGFR), the activation of caspase (specifically, caspase 9, 8, and 3), and the upregulation of pro-apoptotic proteins such as Bax." (PMID 39858410, 2024). "In MCF-7 cells treated with Mel-NIO and olaparib showed non-significant differences between each other in mRNA expression levels of caspase-9 and caspase-3, also non-significant differences in the expression level of caspase-3 between untreated cancer cells and Car-NIO treated cell were detected." (PMID 37808196, 2023). "Additionally, newer generations of CAR-T cells have been modified to include ‘suicide genes’ or switches such as inducible caspase 9, which has been incorporated into MUC1-C-targeted CAR-T cells in an ongoing study of patients with advanced epithelial derived cancers (NCT05239143)." (PMID 37835509, 2023). "Besides this, HSP upregulated some intracellular ROS, ATP, Ca2+ and cytosolic components i,e AIF, Apaf-1, Cyt C, caspase-3, caspase-9, Bax, and down-regulated Bcl-2, mitochondrial AIF, mitochondrial Apaf-1, and mitochondrial Cyt C that mediate apoptosis of cancer cell." (PMID 35128104, 2022). "Other studies indicated that RES induced apoptosis in various cancer cell lines and TNBC cell lines through extrinsic and intrinsic pathways by activating caspase-8 and 9; however, the major pathway of RES is intrinsic through activation of caspase-9-dependent mitochondria pathways." (PMID 35163062, 2022). "Formononetin might induce cancer apoptosis through hydrogen-bonding with CASP3, CASP8, CASP9." (PMID 34955857, 2021). "We concluded that TNFα activates NF-κB activity in cancer cells, which in turn upregulates the pro-apoptotic target gene CAPS9 at the mRNA level and protein level by direct transcriptional regulation, and indirectly decreases the expression of CASP9 repressor miR1276." (PMID 32225068, 2020). "However, it was also suggested that urocortin may have a dual role in cancer, since it differentially binds to CRFR1 or CRFR2 and either activates or blocks the Bcl-2/Bax/caspase-9 axis, leading to apoptosis or survival, respectively." (PMID 31238876, 2019). "Thus, the overexpression of caspase-9 even in drug-sensitive cancer cells deems cells vulnerable to aberrant apoptosis under normal condition." (PMID 29416675, 2018). "The Bcl-2 family of proteins is related to the caspase family of proteins in cancer cell apoptosis and treatment with UDCA increased Bax expression and reduced Bcl-2, Bcl-xL expression, thus possibly affecting the expressions of caspase-3, caspase-8, and caspase-9." (PMID 25951128, 2015).